BRAF (B-Raf proto-oncogene, serine/threonine kinase)
Diseases named in the same sentence as BRAF in open-access papers (continued):
Sharing a sentence is not in itself a finding about the gene and the disease.
tumor (continued). "The response mechanism may involve the establishment of a “drug-free” environment, leading to a decrease in the number of heterogeneous tumor cells previously exposed to BRAF and MEK inhibitors, ultimately resulting in a successful re-challenge for certain patients." (PMID 38731852, 2024). "The use of BRAF inhibitors may affect the interaction between tumor cells and the immune system." (PMID 39529955, 2024). "Several studies have shown that in NSCLC cells with gene alterations of KRAS G12C, BRAF V600E, EGFR, ALK, or ROS1, dysregulation of the Hippo pathway decreases the initial response to various tyrosine kinase inhibitors, which is associated with resistance of targeted therapy and tumor recurrence." (PMID 38499647, 2024). "In addition, BRAF mutation may override the inhibition of Raf1 by PKA and thereby shift the balance between the tumor-promoting and tumor-suppressing effects of cAMP." (PMID 38233872, 2024). "Thus, according to NCCN guidelines, HER2 testing is not indicated if the tumor is already known to have a RAS/BRAF mutation." (PMID 36672503, 2023). "We have shown in this study that, in a cohort of patients residing in the same region and whose tumor specimens were analyzed in the same laboratory, there is likely no racial difference in KRAS mutation frequency, but there is likely a significant racial difference in BRAF mutation frequency." (PMID 38139338, 2023). "However, V600E and G469V enhanced the tumor growth in immunocompetent C57BL/6 mice compared with WT and D594A, suggesting that distinct BRAF mutations may result in alterations of key components of the immune system." (PMID 37853469, 2023). "Interestingly, our data indicate that the loss of primary cilia could potentiate BRAF/MAPK pathway activation, thereby explaining the rapid malignant progression and resistance to therapies of these neoplasms." (PMID 37239344, 2023). "Thus, the evaluation of BRAF mutation status in, for example, 18F-FDG PET/CT-positive metastatic lymph nodes instead of the primary tumour, may have a potential value to be considered for further investigations." (PMID 38201554, 2023). "In addition, BRAF/MEK inhibitors-induced reactivation of MAP kinase signaling by the enhancement of BRAFV600E amplification or alternative splicing, RAS-mutation can also contribute to the development of tumor plasticity." (PMID 37370757, 2023). "If the results of molecular target vectors operating on the Wnt/b-catenin cascade are not yet encouraging, the current literature reports drastic tumor volume reduction associated with good clinical outcomes after oral targeted therapy with BRAF and MEK inhibitors in PCPs." (PMID 36979325, 2023). "The majority of reported cases were published before the advent of molecular biology, reclassified in a wide spectrum of CNS WHO tumour types without a distinct methylation class or more interestingly were midline-located with a co-occurring BRAF and H3-K27M mutations." (PMID 38066305, 2023). "The 7.5-year OS rate of 57% in patients with BRAF-mutant tumours in the nivolumab plus ipilimumab group demonstrates the efficacy of this approach in this population and highlights the question of which might represent the optimal treatment sequencing for these patients." (PMID 37404764, 2023). "In addition to BRAF, the second most common mutation in MAPK pathway is the small GTPase NRAS (25%), and the third is the tumour suppressor and the negative regulator of RAS, neurofibromin 1 (NF1) (14%); both these mutations lead to the activation of the MAPK pathway and increased ERK signalling." (PMID 36967556, 2023).
tumor (continued). "The expression of numerous miRNAs changes before and after treatment in tumour biopsies, highlighting the concept that measurement of miRNA deregulation could allow for the development of tools to predict BRAF-mutant patients’ response or resistance to BRAFi or BRAFi plus MEKi treatment." (PMID 37627054, 2023). "Hence, we sought to exploit the glycolytic dependency of BRAF-driven tumours as a metabolic vulnerability and to adopt new therapeutic approaches to maximise drug efficacy (even at low doses) and avoid—or delay—the onset of secondary resistance and drug-related toxicity." (PMID 37198319, 2023). "CDKN2A and either BRAF or NRAS (non-simultaneously) mutations may occur concurrently within one melanoma tumour, contributing to difficulty in ongoing and initial tumour treatment." (PMID 36614303, 2023). "Moreover, the overexpression of PD-L1 in tumor cells can be due to the activation of signal traducers induced via oncogenic pathways, as has been described in melanoma, with oncogenic BRAF(V600E) signaling inducing IL-1α/β production, with a subsequent upregulation of PD-L1 in the tumor stroma." (PMID 37834467, 2023). "The tumor was negative for other melanocytic markers and was BRAF V600E non-mutated." (PMID 37373134, 2023). "While in normal cells, this would lead to cell cycle arrest, activating mutations in BRAF and NRAS, combined with mutation in tumor suppressors such as PTEN and can result in robust mitogenic signaling and translation of CCND1, which may “override” CDKN1A/p21-mediated checkpoint activation." (PMID 36696495, 2023). "If they represent early-stage tumors in which the BRAF V595E mutation has not yet emerged, then their study has tremendous potential to yield methods for early detection and to identify somatic alterations that drive tumor progression." (PMID 37079639, 2023). "When no targetable mutation is identified (NTRK, ALK, RET or BRAF) or the tumor is not sequenced, the antiangiogenic multi-targeted kinase inhibitors (aaMKIs) Sorafenib, Lenvatinib and Cabozantinib may be used." (PMID 37510219, 2023). "This family includes different tumor types according to their molecular characteristics with different outcomes and signaling pathways altered, non-related to IDH mutations as opposed to their adult counterparts, and frequently associated with an enhanced MAPK pathway and BRAF gene alterations." (PMID 37239036, 2023). "We found that post-treatment samples exhibit resistance to BRAF/MEK inhibition, which is accompanied by elevated expression of markers associated with cancer stem cells, differentiation, and chemo- and radiation-therapy resistance, including CD133, in the post-treatment tumor." (PMID 37920169, 2023). "NTRK inhibitors, such as larotrectinib, may be used after at least one prior line of therapy for those patients who harbour NTRK fusions, which is more commonly seen in MSI-H tumours without RAS or BRAF mutations." (PMID 37377686, 2023). "Thus, BRAF and FGFR1 mutations would be secondary driver events in the oncogenesis of these tumours and could give a proliferative advantage to the H3.3-K27M ancestral clone in a specific developmental window similarly to paediatric LGGs." (PMID 38066305, 2023). "Interestingly, recent data concerning biomolecular characteristics of GS documented that, although GS has a genetic profile that overlaps with GBM and other neoplasms, it is also true that GS has its genetic mutations, such as MSH6, BRAF, SUZ12, SOX2, and FBXW7." (PMID 38202090, 2023). "In addition, BRAF V600E was closely related to tumor development." (PMID 36759818, 2023). "Therefore, when a BRAF V600E mutation is detected in tumors larger than 1cm, a total thyroidectomy is preferred, regardless of other tumor features." (PMID 38201541, 2023).
tumor (continued). "BRAF V600E mutation was positively correlated with the expression of TIM3 in both CRC cells and tumor-infiltrating lymphocytes (TILs) as well as the expression of PD-L1 in tumor cells, suggesting that it might act as an indicator of ICI treatment efficacy in mismatch repair-deficiency (dMMR) CRC." (PMID 37853469, 2023). "Neither BRAF V600E‐mutation nor MLH1‐promotor methylation were identified in tumor tissue." (PMID 36760167, 2023). "Preclinical data suggest that BRAF/MAPK pathway inhibition may augment the tumor immune response." (PMID 36702949, 2023). "Indeed, in the case of recurrent PCP, the tumor shrinking provided by a combination of BRAF and MEK inhibitors as targeted therapy might reduce the morbidity associated to conventional therapeutic options." (PMID 36979325, 2023). "It has been reported that the activation of the signaling cascades associated with BRAF and PTEN mutations, two major alterations frequently found in advanced PTCs, results in thyrocytes in the development of PTC with a fibrotic and reactive tumor stroma in a transgenic mouse model." (PMID 36982542, 2023). "Thus, BRAF interference exerts anticancer effects on the tumour microenvironment." (PMID 37205232, 2023). "The oppositely behaving acidic N-glycan types, especially large, sulfated/phosphorylated, and putative terminal HexNAc containing glycans, showed a clear dependence on tumor stage and BRAF mutation status and may thus be associated with MSI CRC progression according to BRAF mutation." (PMID 37509233, 2023). "A strong correlation was detected between BD and cfDNA concentration in all mutant and negative cases, between the tdDNA concentration and the tumor-derived variant allele frequency (VAF) of BRAF p.V600E, between the tdVAF and the cfVAF in all cases, and between the cfDNA and cfVAF in mutant cases." (PMID 37958315, 2023). "This enabled a unique evaluation of the iodine avidity in primary tumour tissue, resected lymph node metastases, and comparison of avidity to the expression of iodine-transport related proteins (NIS, TPO, TSHR and pendrin), as well as mutations in the TERT promoter and codon V600 of the BRAF gene." (PMID 37352166, 2023). "Tumours with BRAF-mutations might therefore direct early to a mesenchymal phenotype while tumours with KRAS-mutations might develop without EMT." (PMID 37344790, 2023). "However, the exact mechanism linking aberrant HES1 expression to KRAS/BRAF mutant tumor invasion and metastasis remains unknown." (PMID 37749297, 2023). "The BRAF mutation causes constitutive activation of the MAPKP, which leads to the high activating capacity of the MAPK pathway after a cascade of phosphorylation in the transcription of genes enhancing the differentiation, proliferation, inhibition of apoptosis, and survival of tumor cells." (PMID 38202120, 2023). "We included BRAF V600E mutation, which is the most representative molecular signature in PTC, as a variable in this study and revealed similar results as once widely reported: BRAF V600E mutation occupied up to 2/3 of all cases and is of great potentials in predicting tumor recurrence." (PMID 36651705, 2023). "Thus, the finding that BRAFi/diclofenac combinations exert a potent anti-tumour activity even at very low BRAFi doses in both PTC and ATC BRAF-mutated cell lines strongly suggests the possibility to delay—or reduce—the onset of acquired resistance, limiting the risk of unwanted effects." (PMID 37198319, 2023). "However, the targeted BRAF therapy alone is not very effective, and it was reported to be associated with the persistence of a high level of tumor PDL1 expression." (PMID 36673047, 2023).
tumor (continued). "The activation of BRAF-V600E also results in phosphorylation of the inhibitor of kappa B (IκB) leading to its ubiquitin-proteasome-dependent degradation and the release of NF-κB that can now translocate to the nucleus and upregulate tumor-promoting and anti-apoptotic genes." (PMID 35406382, 2022). "MLH1 promoter methylation is associated with a specific BRAF mutation (V600E) which is therefore used as an additional parameter for excluding patients from genetic testing since the tumor MSI in these cases is unlikely to result from a germline MMR gene inactivation." (PMID 36454741, 2022). "This included collating studies of Sanger sequencing hot spot regions in BRAF, NRAS, and KIT, identifying rare but recurrent functionally relevant non‐hot spot variants, which otherwise would not have been uncovered, highlighting the importance of analyzing larger tumor collections." (PMID 35229492, 2022). "Thus, combining KDs with BRAF/MEK or PI3K inhibitors may synergize with the tumor-reductive effect exerted by KDs as a monotherapy in our study." (PMID 35851093, 2022). "In a melanoma study, CCR4 was required for the homing Tregs to nascent tumor sites from LNs, and BRAFV600E signaling controlled the expression of CCR4 chemokines, raising the possibility that inhibiting this signaling with BRAF inhibitors may have reduced Treg recruitment to the tumor." (PMID 34417572, 2022). "Thus, this combination strategy could be effective in a clinical application as it allows the suppression of the stromal fibrotic‐like reaction induced by oncogenic BRAF pathway inhibition and prevents tumor relapse." (PMID 34957688, 2022). "The overall detection rate was 62% and was independent of the tumour BRAF mutational status." (PMID 34373567, 2022). "The discrepancy between preclinical laboratory experiments and observations made in the clinic could be explained by the fact that some KRAS wt tumours can still activate the RAS pathway due to events other than RAS oncogene mutations, such as BRAF or EGFR mutation." (PMID 36163168, 2022). "Recently, studying reports suggest that BRAF non-V600E tumours may be sensitive to EGFR inhibitors." (PMID 36819812, 2022). "In addition to the improvement of neurological symptoms and high local tumor control rates with radiation therapy, there may be synergy between BRAF plus MEK inhibitors and radiation." (PMID 36579260, 2022). "We hypothesize that KRAS and BRAF mutations are unlikely to develop within the same lesion given differences in allele frequencies and may reflect tumour heterogeneity detected by the F1L CDx assay." (PMID 35338679, 2022). "Moreover, in several cases of SLN, it cannot be performed because it cannot meet the supplier’s recommendations (especially regarding the tumor sample size and the % of TC), although our results suggest that 10% TC is appropriate for the detection of BRAF V600E." (PMID 35328303, 2022). "Additionally, there was quite a large proportion of missing data on some of the baseline characteristics (such as Breslow thickness or BRAF status), partly explained because the primary tumour was unknown, and BRAF status was registered only after 2017." (PMID 36230827, 2022). "Compared to the initial grossly resected tumor specimen, the recurrent tumor possessed loss of heterozygosity of 1p, 10q, 17q, and 19q chromosomes, as well as a new C228T TERT promoter mutation, while the status of wild-type IDH1/IDH2 and mutant BRAF V600E was unchanged." (PMID 36703629, 2022).
tumor (continued). "Since BRAF V600E mutations are currently considered an agnostic genetic alteration and seem to respond to BRAF inhibitors regardless of the primary tumor type, we recommend a BRAF inhibitor with or without a MEK inhibitor to patients with unresectable or metastatic BRAF mutant GISTs." (PMID 36358751, 2022). "PDX CRC models maintain important gene mutations such as KRAS, BRAF (v-Raf murine sarcoma viral oncogene homolog B), PIK3CA (Phosphatidylinositol-4, 5-bisphosphate 3-kinase), gene expression, copy number changes, and microsatellite instability of the primary tumor." (PMID 35538576, 2022). "Simultaneous existence of BRAF missense mutation and an APC truncation was rarely observed, which further supported the hypothesis that the most important oncogenic driver events differed between Wnt‐low and Wnt‐high tumor groups." (PMID 35904277, 2022). "Interestingly, patients previously treated with BRAF inhibitors had a worse response in terms of tumor size and progression-free survival, suggesting that BRAF inhibition-resistant mechanisms activate cancer-related reprogramming of the cell in such a way that MEK inhibitor sensitivity is lower." (PMID 36358912, 2022). "As BRAF and PIK3CA mutations tended to co-occur in the ATC tumours, we hypothesized that the introduction of a PIK3CA mutation into a BRAF mutant PTC model would lead to increased aggressiveness and cellular dedifferentiation, mimicking a possible route of progression from PTC to ATC." (PMID 35193694, 2022). "First, as some mutations may be enriched in some tumor types, the original goal of this study was to create a panel rather than identify a single gene (such as BRAF), as the former can include more genes to predict prognosis across different types of tumors." (PMID 35197093, 2022). "Despite preclinical data supporting the immunomodulatory effects of BRAF/MEK inhibitors in the tumor microenvironment, clinical and preclinical data suggest that this effect might be transient and that acquired resistance to BRAF/MEK inhibitors is suggestive of a cross-resistance to ICIs as well." (PMID 36428582, 2022). "Importantly, BRAF P1, with multiple miRNA binding sites, can regulate the expression of its parental gene by sequestering specific miRNAs through a competitive endogenous RNA mechanism, and this specificity depends on the tumor type." (PMID 36139427, 2022). "This suggests that excessive tumor-generated HB-EGF might prevent PEPDG278D from binding to EGFR, and also suggests that EGFR signaling remains important to the tumors carrying activating mutations of KRAS, BRAF and/or PIK3CA." (PMID 35650607, 2022). "Nevertheless, a correct diagnosis of CM metastases is mandatory, because cytological samples may also be used for the predictive evaluation of the BRAF molecular status of the neoplasm, and because immunotherapy has recently been introduced for patients affected by metastatic CM." (PMID 35328198, 2022). "For example, DUSP4 is noted as a tumor suppressor due to its role in inhibiting MAPK signaling; however, we find increased dependency on DUSP4 in cell lines with activating mutations in BRAF suggesting that DUSP4 contributes to maintaining the balance of MAPK signaling in BRAF mutant tumors." (PMID 35382456, 2022).